INHBA (inhibin subunit beta A)
Description:
Inhibins/activins are involved in regulating a number of diverse functions such as hypothalamic and pituitary hormone secretion, gonadal hormone secretion, germ cell development and maturation, erythroid differentiation, insulin secretion, nerve cell survival, embryonic axial development or bone growth, depending on their subunit composition. Activin A is a homodimer of INHBA that plays a role in several essential biological processes including embryonic development, stem cell maintenance and differentiation, haematopoiesis, cell proliferation and tissue fibrosis. Signals through type I (such as ACVR1B or ACVR1C) and type II receptors (such as ACVR2A, ACVR2B or BMPR2) which, upon ligand binding, phosphorylate SMAD2 and SMAD3 intracellular signaling mediators that form a complex with SMAD4, translocate to the nucleus and modulate gene expression. Can also activate alternative non-canonical intracellular signaling pathways including the p38 MAPK, extracellular signal-regulated kinases 1/2 (ERK1/2) and c-Jun N-terminal kinases (JNKs) to modulate cell migration and differentiation. Alternatively, promotes osteoblastic differentiation via ACVRL1-SMAD1/5/9 pathway. In addition, can engage the type I receptor ACVR1 to form an ACVR1-activin A-type II receptor non-signaling complex (NSC) that renders receptors unavailable for engagement with BMPs, hence resulting in an apparent inhibition of ACVR1-mediated BMP signaling. Inhibin A is a dimer of alpha/INHA and beta-A/INHBA that functions as a feedback regulator in the hypothalamic-pituitary-gonadal (HPG) axis. Inhibits the secretion of FSH from the anterior pituitary gland by acting on pituitary gonadotrope cells. Antagonizes activin A by binding to the proteoglycan, betaglycan, and forming a stable complex with and, thereby, sequestering type II activin receptors while excluding type I receptor.
Synonyms: EDF; FRP
Tractability: Small molecule: a structure with a bound ligand is known. Antibody: a drug acting on it is in phase 2 or 3 trials; UniProt places it where antibodies can reach, with high confidence; its Gene Ontology location is reachable by antibodies, with high confidence; UniProt predicts a signal peptide or a membrane-spanning region. PROTAC: ubiquitination databases record sites on it. Other modalities: a drug acting on it is in phase 2 or 3 trials.
Target class: Secreted protein
Gene: Protein-coding gene on chromosome 7 (41,667,168 to 41,705,834, reverse strand). Ensembl gene ENSG00000122641.
Subcellular location: Secreted
Pathways (Reactome):
Signal Transduction: Antagonism of Activin by Follistatin; Signaling by Activin; Signaling by BMP; TGFBR3 regulates activin signaling
Metabolism of proteins: Glycoprotein hormones
Gene Ontology:
Molecular function: cytokine activity; identical protein binding; peptide hormone binding; protein binding; protein sequestering activity; type II activin receptor binding; growth factor activity; hormone activity; protein-containing complex binding; signaling receptor binding
Biological process: activin receptor signaling pathway; endodermal cell differentiation; extrinsic apoptotic signaling pathway; GABAergic neuron differentiation; hair follicle development; hematopoietic progenitor cell differentiation; hemoglobin biosynthetic process; male gonad development; negative regulation of activin receptor signaling pathway; negative regulation of cell growth; negative regulation of cell population proliferation; negative regulation of G1/S transition of mitotic cell cycle; odontogenesis; ovarian follicle development; positive regulation of DNA-templated transcription; positive regulation of erythrocyte differentiation; positive regulation of extrinsic apoptotic signaling pathway in absence of ligand; positive regulation of gene expression; positive regulation of protein metabolic process; positive regulation of SMAD protein signal transduction; positive regulation of transcription by RNA polymerase II; progesterone secretion; regulation of follicle-stimulating hormone secretion; regulation of transcription by RNA polymerase II; roof of mouth development; and 33 more
Cellular component: activin A complex; extracellular region; inhibin A complex; plasma membrane; perinuclear region of cytoplasm
Genetic constraint (gnomAD): Loss-of-function variants: 1 observed, 28.63 expected, observed/expected ratio (o/e) 0.0349, 90% interval 0.011 to 0.17. The upper end of that interval is the gene's LOEUF score, 0.17, which puts it in group 1 of 6, group 1 being the genes least tolerant of losing a copy. Missense variants: 376 observed, 561.5 expected, observed/expected ratio (o/e) 0.67, 90% interval 0.62 to 0.73. Synonymous variants: 242 observed, 228.09 expected, observed/expected ratio (o/e) 1.06, 90% interval 0.95 to 1.18.
Homologues: Orthologues: chimpanzee INHBA (100% identical), macaque INHBA (99% identical), rabbit INHBA (97% identical), mouse Inhba (96% identical), rat Inhba (96% identical), pig INHBA (92% identical), dog INHBA (92% identical), tropical clawed frog inhba (69% identical), zebrafish inhbab (55% identical), zebrafish inhbaa (52% identical). Paralogues in human: INHBB (41% identical), INHBC (30% identical), INHBE (28% identical), BMP7 (21% identical), BMP6 (21% identical), TGFB3 (20% identical), BMP5 (20% identical), BMP10 (19% identical), BMP4 (19% identical), BMP8A (19% identical), BMP8B (19% identical), MSTN (19% identical), and 19 more.
Diseases named in the same sentence as INHBA in open-access papers:
INHBA is named in the same sentence as 126 diseases in open-access papers, as found by Europe PMC text mining. Sharing a sentence is not in itself a finding about the gene and the disease. The quoted sentences say what the papers report.
gastric cancer (39 papers, 2007 to 2026). A primary or metastatic malignant neoplasm involving the stomach. "By analyzing gene expression patterns through single-cell RNA sequencing, we found that several key genes, including SPARC, THBS2, COL1A1, and INHBA, are linked to poor prognosis in gastric cancer." (PMID 40075643, 2025). "Kumar et al17 recently suggested that the presence of a FAP+ and INHBA+ CAF subset is associated with poor prognosis of gastric cancer through single-cell transcriptomic analysis." (PMID 37196797, 2023). "Aberrant methylation and differential expression of INHBA are associated with prognosis in gastric cancer, based on RNA-Seq and Illumina Human Methylation 27 Chip data from the TCGA database." (PMID 35216189, 2022). "Studies have reported that INHBA is up-regulated in gastric cancer and linked to poor survival, INHBA gene silencing can gives a potential target in the treatment of gastric cancer." (PMID 31586103, 2019). "INHBA, Inhibin- βA (INHBA), a ligand belonging to the transforming growth factor- β superfamily, is associated with cell proliferation in various tumor types including colon adenocarcinoma, pancreatic cancer, gastric cancer as well as oral squamous cell carcinoma." (PMID 33717664, 2021). "To elucidate the biological functions of INHBA in gastric cancer, we employed the HGC-27 and AGS cell lines to establish INHBA-knockdown models." (PMID 39543755, 2024). "For example, INHBA is negatively correlated with B-cell infiltration and positively with macrophages, neutrophils and dendritic cells in gastric cancer." (PMID 39006030, 2024). "Recent research has reported that INHBA participates in the migration and invasion of gastric cancer cells by regulating the TGF-β signaling pathway." (PMID 37940978, 2023). "The expression level of INHBA in various malignant tumor tissues, such as gastric cancer and breast cancer, is significantly increased." (PMID 36984496, 2023). "Silencing INHBA inhibits invasion and migration in gastric cancer through the TGF-β signaling pathway." (PMID 37940978, 2023). "A functional role for INHBA in gastric cancer CAFs has also been demonstrated by a recent study in gastric cancer that used bulk RNA-seq of laser-capture microdissection (LCM)–derived CAF samples." (PMID 34642171, 2022). "We also added CXCL12, INHBA, THBS1, and THBS2 to the correlation analysis since they are suggested as CAF markers associated with an aggressive phenotype in gastric cancer." (PMID 35739492, 2022). "As an indicator of poor prognosis, researchers found that the expression of INHBA was positively correlated with tumor diameter and infiltration in gastric cancer." (PMID 35236827, 2022). "Overexpression of INHBA has been reported in several malignant tumors such as lung cancer, esophageal adenocarcinoma, gastric cancer, prostate cancer, and urothelial carcinoma." (PMID 35216189, 2022). "To assess the clinical relevance of our findings, we mapped FAP and INHBA expression levels across the gastric cancer cohort." (PMID 34642171, 2022). "Previous findings have observed that INHBA downregulation led to diminutions in the invasion and proliferation of some cancer cells, such as prostate cancer stem cells and gastric cancer cells." (PMID 35236827, 2022). "Clinically, patients with high INHBA-expressing tumors exhibited poorer survival outcomes in multiple gastric cancer cohorts, consistent with a tumorigenic function for INHBA." (PMID 34642171, 2022). "Taken collectively, these results highlight INHBA as a positive regulator of FAP in the gastric cancer STF3 fibroblast population." (PMID 34642171, 2022). "In recent years, more and more evidence showed that the high expression of INHBA was related to the occurrence and development of various malignant tumors, such as ovarian cancer, gastric cancer, pancreatic cancer, and CRC." (PMID 35236827, 2022).
gastric cancer (continued). "Overexpression of the INHBA gene is considered a useful independent predictor of outcomes in patients with gastric cancer after the curative surgery." (PMID 33828156, 2021). "The upregulation of INHBA was also reported in other cancers by previous studies, such as gastric cancer, esophageal adenocarcinoma and colorectal cancer." (PMID 34346300, 2021). "Many studies have demonstrated the prognostic role of INHBA in colon adenocarcinoma, and the role of INHBA in gastric cancer has been widely reported also." (PMID 33717664, 2021). "Compared with normal tissues, ADAM12, CEP55, LRFN4, and INHBA were up-regulated in gastric cancer samples, while ADH1B, DPT, FAM107A, and LOC100506388 were downregulated." (PMID 34686626, 2021). "Previous researches have demonstrated that the expression of INHBA is related with prognosis of different types of cancer, such as lung cancer, colorectal cancer, gastric cancer, urothelial carcinoma, and breast cancer." (PMID 31827640, 2019). "Among the over-expressed transcripts in colorectal lesions, INHBA has been already identified in the transition from CRA to CRC, and its expression has been associated with different cancers, especially with gastric cancer." (PMID 24516561, 2014). "We found that inhibin β A subunit (INHBA) mRNA is overexpressed in gastric cancer (GC) specimens and investigated the effect of activin A, a homodimer of INHBA, on angiogenesis in GC." (PMID 21897392, 2011). "Recent studies comparing gastric cancer and normal tissue have identified a number of genetic markers, including diagnostic markers [NF2, INHBA, SFRP4], prognostic markers [CD9, CDH17, PDCD6], and gastric cancer-associated genes [MUC13, CLDN1, Ki67 and CD34]." (PMID 22133303, 2011). "Western blotting showed strong bands for both NEK6 and INHBA in gastric cancer tissues compared to normal tissue in all three pairs." (PMID 18827816, 2008). "Furthermore, the Edu assay confirmed that the knockdown of INHBA inhibited gastric cancer cell growth in vitro." (PMID 39543755, 2024). "It has been reported that INHBA expression detected in gastric tumor tissue has increased at least twofold compared to adjacent normal tissue, and INHBA gene silencing is able to inhibit gastric cancer cell migration and invasion through the transforming growth factor β signaling pathway." (PMID 36984496, 2023). "Therefore, the level of INHBA is significantly increased in malignant tumors, such as gastric cancer, nasopharyngeal cancer, colorectal cancer and cervical cancer, and its high expression is closely related to the poor prognosis of patients." (PMID 36984496, 2023). "Furthermore, INHBA silencing inhibits the migration and invasion of gastric cancer cells by blocking TGF-β signaling." (PMID 37940978, 2023). "INHBA overexpression has been correlated with aggressive phenotype in different cancers, including colorectal cancer, lung adenocarcinoma, esophageal adenocarcinoma, ovarian cancer, and gastric cancer." (PMID 34346300, 2021). "One study has demonstrated that INHBA gene silencing could inhibit gastric cancer cell migration and invasion by impeding TGF- β signaling pathway." (PMID 33717664, 2021). "Additionally, INHBA gene is found to mediate activation of the TGF-β signaling pathway to promote gastric cancer cell migration and invasion." (PMID 31827640, 2019). "Interestingly, recent study revealed that TGF-β signalling including INHBA accounted for some of the main differences between normal tissue and gastric cancer at the transcript level." (PMID 18827816, 2008). "INHBA is a member of TGF-β superfamily and can accelerate migration and invasion of gastric cancer cells via TGF-β signaling pathway." (PMID 37377935, 2023). "Functionally, silencing of INHBA affected FAP levels in gastric cancer CAFs, implying a potentially direct role for INHBA in regulating FAP expression, and consistent with TGFβ signaling as a mediator of INHBA." (PMID 34642171, 2022).
gastric cancer (continued). "INHBA and INHBB showed similar correlations with survival in gastric cancers, specifically HER2+, and renal papillary cell carcinoma." (PMID 33819300, 2021). "The stage-based assessment of overexpressed genes showed significant upregulation of CST1, INHBA, ACAN, HSP90AB1, and HSPD1 genes across all stages, including early, locally advanced and metastatic stomach cancer." (PMID 33828156, 2021). "Comparison between normal stomach tissue and stomach tumors showed that CST1 (p = 3.97E−21), INHBA (p = 9.22E−20), ACAN (p = 1.08E−19), HSP90AB1 (p = 2.62E−19), and HSPD1 (p = 3.91E−19) were the leading five genes that were overexpressed in stomach cancer." (PMID 33828156, 2021). "INHBA gene silencing has been reported to be able to inhibit cell migration and invasion by TGF-β signaling pathway in gastric cancer." (PMID 34889158, 2021). "Our analysis showed that compared with normal stomach tissue, CST1, INHBA, ACAN, HSP90AB1, and HSPD1 were the leading five genes that were overexpressed in stomach cancer." (PMID 33828156, 2021). "The upregulation of FAP and INHBA in gastric cancers rather than precancerous lesions is a strong indicator of the upregulation of specific mediators in fibroblasts, especially in association with frank cancers." (PMID 38825636, 2024). "For example, two protumorigenic proteins, inhibin subunit beta A (INHBA) and thrombospondin 2 (TSP2), are secreted from CAFs to the TME via extracellular vehicles, found to be an HSF1-dependent mechanism that promotes gastric cancer." (PMID 37153737, 2023). "In particular, NEK6 and INHBA are promising potential markers of gastric cancer regardless of disease stage." (PMID 18827816, 2008). "Three of these are known to be involved in gastric cancer: MMP7, SPARC, and SOD2, and the other four have no such reported associations (INHBA, IGFBP7, NEK6, and LUM)." (PMID 18827816, 2008). "Genes, such as CHAF1B, INHBA, TGFB2, SKA3, and HELLS, are responsible for the invasion of various cancer cells, such as hepatocellular carcinoma, gastric cancer cells, renal cell carcinoma, prostate cancer, head and neck cancer, but these genes may be involved in the invasion of BRCA cells." (PMID 31311202, 2019). "In conclusion, we showed that a combination of expression of PDGFRB, INHBA, MMP11, and galectin-10 in GC tissues may serve as a useful biomarker for survival stratification in patients with pStage II/III gastric cancer following curative resection." (PMID 36139587, 2022).
breast carcinoma (31 papers, 2009 to 2025). "Here, we comprehensively evaluated INHBA expression and the association between INHBA levels and breast cancer patients' prognosis in public databases such as Oncomine, Kaplan–Meier plotter, and PrognoScan." (PMID 36304286, 2022). "Our findings reveal that high expression of INHBA was an adverse prognostic biomarker for breast cancer and provide an underlying mechanism between INHBA and tumor–immune interactions." (PMID 36304286, 2022). "INHBA expression in breast cancer tissues is closely associated with collagen production." (PMID 41008625, 2025). "Conclusively, it is believable that high INHBA expression could be a risk factor for a poor prognosis in breast cancer patients." (PMID 36304286, 2022). "Interestingly, we also found that INHBA expression was associated with the level of immune infiltration in breast cancer." (PMID 36304286, 2022). "However, Kaplan–Meier survival analysis showed a strong association of high co‐expression of mDia2/DIAPH3 and INHBA with decreased survival of patients with liver, stomach, and breast cancer." (PMID 32150356, 2020). "To determine if activin may have a role in breast cancer, we examined several publicly available gene expression datasets and found that the gene encoding the activin A subunit, INHBA, is upregulated in the majority of breast tumors compared with normal breast tissue in three independent datasets." (PMID 28583174, 2017). "Interconversion of differentiated breast cancer cells into stem cells also requires activin/nodal signaling, and one of the most predictive genes within a core metastasis-associated expression signature of multiple cancers is INHBA, which encodes an activin and inhibin subunit." (PMID 28583174, 2017). "This study analyzed the TCGA database and found that FAP and INHBA were significantly positively correlated with breast cancer." (PMID 41008625, 2025). "The clinical relevance of INHBA expression with breast cancer was analyzed by using the TCGA database." (PMID 41008625, 2025). "Through in-depth analysis of single-cell sequencing data from breast cancer tissues, we found that there were significant individual differences in the expression levels of INHBA in CAFs from different patient sources." (PMID 41008625, 2025). "INHBA expression is suggested to correlate with macrophage infiltration in cervical cancer and breast cancer." (PMID 38480935, 2024). "Recent studies have shown that INHBA is elevated in breast cancer tissues and promotes the metastasis of breast cancer cells." (PMID 37940978, 2023). "In breast cancer cells, downregulation of INHBA can delay the growth of primary tumors, inhibit the migration of tumor cells, and reduce the possibility of lung metastasis." (PMID 36984496, 2023). "Study also revealed that INHBA plays a functional role in supporting EMT phenotype of breast cancer cells." (PMID 37940978, 2023). "In breast cancer, INHBA reportedly induces epithelial-mesenchymal transition by activating the TGF-β signaling pathway." (PMID 36348017, 2023). "Analysis of breast cancer datasets showed that patients with HER2+ breast cancer and high levels of INHBA expression had worse outcomes than patients with low levels of INHBA expression." (PMID 35248133, 2022). "The cell experiment results suggested that NFKBIA played a protective role, while INHBA played the pro-cancer role in breast cancer." (PMID 35999846, 2022). "We examined expression of INHBA in large public datasets to determine the impact of high levels of expression on outcome in breast cancer." (PMID 35248133, 2022). "It is worth mentioning that in addition to CRC, INHBA is highly expressed in various tumor tissues, such as breast cancer and esophageal squamous cell carcinoma." (PMID 35236827, 2022). "Conversely, age and basal-like status were negatively related to INHBA level in breast cancer samples with respect to normal tissues." (PMID 36304286, 2022).